MMP14 (matrix metallopeptidase 14)
Diseases named in the same sentence as MMP14 in open-access papers (continued):
Sharing a sentence is not in itself a finding about the gene and the disease.
breast carcinoma (continued). "Accordingly, it has been reported that several other MMPs and TIMPs may be overexpressed and/or related to clinical outcome in breast cancer, such as MMP-11 MT1-MMP (MMP-14) MMP-13, TIMP-1 or TIMP-2." (PMID 17848954, 2007). "This prompted us to test the hypothesis that the individual expression or the balance between MMP-2, MMP-14 and TIMP-2 expression may help to predict breast cancer prognosis." (PMID 16776850, 2006). "Further Kaplan–Meier plotter results indicated that in both breast cancer subtype cases, the higher expression of MMP14 showed a clear but not statistical trend for correlation with lower OS probability of patients’ OS (p = 0.065 in Luminal A and p = 0.053 in TNBC, respectively)." (PMID 41228316, 2025). "The expression of MMP2 and MMP14 in human breast cancer samples was detected using IHC, and the results showed that GABARAP negatively correlated with MMP2 and MMP14, which indicates that GABARAP also inhibits invasion and metastasis in human breast cancer samples." (PMID 33591943, 2021). "The SYK inhibitor, BI 1002494, caused no increase in proliferation in breast cancer cells or primary mammary epithelial cells in 2D or 3D cultures, nor changes in proliferation (CD1/2, CDK4, PCNA, Ki67) or invadopodia markers (MMP14, PARP, phospho-vimentin Ser56)." (PMID 32292575, 2020). "Prompted by our findings demonstrating clear colocalization of CAIX with integrins and MMP14 at the leading edges of cells, we performed chemotaxis and wound-induced migration assays to investigate the functional contribution of CAIX to the migration of breast cancer cells." (PMID 28692057, 2017). "In breast cancer cells, MMP-14 modulates DNA damage response through extracellular integrinβ1 signaling, whereas MMP-14 knockdown in ACC cells did not affect integrinβ1 downstream targets, as evidenced by unchanged AKT and ERK phosphorylation." (PMID 41542511, 2026). "DAB2, MMP14, and SPP1 were also consistently expressed in CD68+ microglia/macrophages in patient-derived breast cancer BrM (n = 4), while their expression was absent from the patient-matched blood." (PMID 31501884, 2020). "For example, breast cancer cell networks upregulated VEGFA fold change = 1.65 and MMP14 fold change = 1.72, but fibrosarcoma cell networks did not." (PMID 29162797, 2017). "MMP-2, MMP-14 and TIMP-2 expression has been evaluated by 35S mRNA in situ hybridization on paraffin material of 539 breast cancers without distant metastasis at diagnosis and with a median follow-up of 9.2 years." (PMID 16776850, 2006). "However, clinical studies on breast cancer are rare, limited in size and do not address the potential interaction of all three factors (MMP-2, MMP-14 and TIMP-2)." (PMID 16776850, 2006).
glioma (133 papers, 1999 to 2025). A benign or malignant brain and spinal cord tumor that arises from glial cells (astrocytes, oligodendrocytes, ependymal cells). "MMP-2, MMP-9, and MMP-14 are particularly implicated in BBB degradation in gliomas, where their activity weakens tight junctions between endothelial cells and facilitates tumor invasion into the brain parenchyma." (PMID 40265458, 2025). "Elevated expression of IL-6 and MMP14 are strongly associated with reduced survival rates, particularly in high-grade gliomas." (PMID 40345526, 2025). "MMP14 works through a specific crosstalk mechanism in which glioma-associated microglia upregulate TLR2, and glioma cells increase the expression of TLR2 ligand versican." (PMID 38473812, 2024). "Previously, miR-584-3p was confirmed to direct target Rho-associated, coiled-coil containing protein kinase 1 in glioma, matrix metallopeptidase 14 in gastric cancer, structure specific recognition protein 1 in colorectal cancer." (PMID 37305398, 2021). "Taken together, our findings demonstrated that in diffuse IDH-mutated gliomas, tumor cells represent the major sources of MMP14, -16, and -17, providing a rationale for functional analyses of MT-MMPs in glioma cells." (PMID 32872536, 2020). "One approach is to target the highly expressed MMP14 in human glioma cells using an oncolytic adenovirus encoding an MMP14-silencing small hairpin RNA (shRNA), CRAd-S-5/3shMMP14." (PMID 33167307, 2020). "The membrane-type 1 matrix metalloproteinase (MMP-14) is a pro-tumorigenic factor: its upregulation is associated with glioma expansion." (PMID 28993312, 2017). "For instance, human astrocytes secrete IL-6, which in turn up-regulate the expression of matrix metalloproteinase-14 (MMP14) in glioma cells." (PMID 40345526, 2025). "This probe combines a PET radionuclide with near-infrared fluorescence (NIRF) dye, activating the fluorescent signal upon MMP-14 cleavage, improving the visualization and differentiation of glioma cells." (PMID 39911388, 2025). "M2 TAMs enhance glioma invasion via TLR2-induced matrix metalloproteinase-14 (MMP-14)/MMP-2 expression and support GSC proliferation, epithelial–mesenchymal transition (EMT), and therapy resistance." (PMID 40948940, 2025). "Transfection of full-length BAI1 cDNA in glioma cells showed that the ~ 150–160 kDa band represents an isoform with a shortened N terminus, likely due to MMP14 cleavage of FL-BAI1." (PMID 38941066, 2025). "IR also sufficiently increased expression of MMP14 in glioma cells (as well as in other cancer cell lines), and inhibition of MMP14 made these cells more sensitive to irradiation." (PMID 41516288, 2025). "Beyond VEGFA, IGF2BP2 can also indirectly regulate hypoxia-inducible factor 1 subunit alpha (HIF1A) and matrix metalloproteinase 14 (MMP14) to drive vasculogenic mimicry in glioma." (PMID 39596216, 2024). "This is accompanied by an upregulation of its TLR1 and TLR2 expression and mediates an increase in MMP-9/MMP-14 expression, promoting microglia-mediated glioma progression." (PMID 37700840, 2023). "The main mechanism that contributes to glioma invasiveness is the degradation of the surrounding extracellular matrix by matrix metalloproteases (MMPs), especially MMP14." (PMID 36768141, 2023). "MMP-14 is of particular interest due to its involvement in the progression of gliomas, with elevated levels in these tumors and important functions in growth, invasion, migration, and angiogenesis." (PMID 38003553, 2023). "By decreasing cell growth and enhancing cellular proliferation, vanillin at a dose of 100 μM can decrease TLR2 expression and increase the expression of MMP‐9, MMP‐14, IL‐6, and iNOS expression in the glioma cell line GL261 at a dose dependent." (PMID 37675821, 2023). "In glioma, it induces cell invasion by modulating MMP-14 and uPAR expression via its direct target HOXD10." (PMID 37398551, 2023).
glioma (continued). "Western blot also showed that the protein levels of CALCRL, SERPINE1, and MMP14 in glioma cells were basically higher than human glioma cells, whereas GABBR1 has the opposite trend, which is consistent with the results qRT-PCR and IHC." (PMID 37488455, 2023). "The western blot results also confirmed the differences of CALCRL, GABBR1, SERPINE1, and MMP14 in normal human astrocyte cell and glioma cells." (PMID 37488455, 2023). "Further, the functions of TIAR, LOXL1‐AS1, miR‐374b‐5p and MMP14, and their interactions in modulating cellular behaviours and VM in glioma are yet to be established." (PMID 34890108, 2022). "First, the expressions of TIAR, the lncRNA LOXL1‐AS1, miR‐374b‐5p and MMP14 were examined by qRT‐PCR and Western blot in both, glioma tissues and glioma cell lines." (PMID 34890108, 2022). "To figure out its role in gliomas, we assessed the effects of diverse transfections altering MMP14 expressions on the malignant cell behaviour." (PMID 34890108, 2022). "We also noticed that miR‐374b‐5p restrained MMP14 by binding to its 3′UTRs according to the dual‐luciferase reporter assay and Western blot, leading to the inhibition of VM by glioma cells." (PMID 34890108, 2022). "In summary, we demonstrated that TIAR combined with LOXL1‐AS1 modulates VM in glioma via the miR‐374b‐5p/MMP14 axis, revealing novel targets for glioma therapy." (PMID 34890108, 2022). "As already mentioned, TIAR interacts with LOXL1-AS1 to modulate vasculogenic mimicry in glioma via the miR-374b-5p/MMP14 axis." (PMID 35887183, 2022). "Proliferation, migration, invasion and tube formation assays were conducted to evaluate the roles of TIAR, LOXL1‐AS1, miR‐374b‐5p and MMP14 in malignant cellular behaviours in glioma cells." (PMID 34890108, 2022). "TLR2 promotes GAM production of MMP14, which is essential for MMP2 release and glioma invasion, and microglial expression of MT-MMP, which cleaves proMMP2 into its active form, leading to tumor invasion." (PMID 35448036, 2022). "IGF2BP2 enhances the stability of OIP5-AS1, thereby increasing the binding of OIP5-AS1 to miR-495-3p, weakening the binding of miR-495-3p to the 3'UTR of HIF1A and MMP14 mRNA, and ultimately promoting the formation of VM in glioma." (PMID 34345216, 2021). "Initially, we explored the mRNA expression of MMP2, MMP9 and MMP14 in the human glioma cell lines T98G, U87MG, U138MG, U251MG and A172 by real time RT-qPCR." (PMID 33919029, 2021). "MMP14 is upregulated in GAMs, and its expression correlates with the increased tumor growth in murine glioma models." (PMID 34504786, 2021). "And some researchers found that the mechanism of MMP14 in glioma mainly works by cutting CD44, or via the combination of TIMP-2 and MMP14 to activate MMP-2 and MMP9 to enhance tumor invasion and tumor cell proliferation." (PMID 34712139, 2021). "The expression of both MMP2 and MMP14 are significantly increased in grade IV GBMs in comparison with lower grade gliomas." (PMID 33919029, 2021). "CCK-8 assays, cell transwell assays, and three-dimensional cell culture methods were used for evaluating the function of IGF2BP2, OIP5-AS1, miR-495-3p, HIF1A and MMP14 in biological behaviors of glioma cells." (PMID 34345216, 2021). "In glioma and melanoma cells, MMP14 and integrin αVβ3 colocalized in the cytoplasm as indicated by IF staining." (PMID 32352029, 2020). "Our findings are in line with several reports of MMP14 expression in glioma cells and most glioma cell lines." (PMID 32872536, 2020). "We discovered that microglial cells express MMP14 as a membrane bound protein which serves to activate glioma released MMP2." (PMID 32331440, 2020). "O-Vanillin was able to attenuate the glioma-induced increase in mmp14 and mmp9 in cultured microglia as well as in microglia/macrophages isolated from human glioma samples." (PMID 32331440, 2020).
glioma (continued). "MMP14 enhances the proliferation and migration of human U251 glioma cells and elevates the expression of vascular endothelial growth factor (VEGF) in vitro." (PMID 32872536, 2020). "In a later report, it was demonstrated that microglial MMP14 enables murine GL261 glioma cells to migrate in murine organotypic brain-slice cultures." (PMID 32872536, 2020). "By cleaving tissue transglutaminase (tTG), MMP14 alters the migratory potential of U251 glioma cells, producing increased migration on collagen and decreased migration on fibronectin." (PMID 32872536, 2020). "MMP-14 (MT1-MMP) is most often studied in the brain in the context of gliomas, where it is highly expressed along other MMPs." (PMID 31172215, 2019). "It has been shown that the activity of certain matrix metalloproteases, such as MMP-2 (gelatinase A), MMP-9 (gelatinase B), MMP-14 (matrix metalloproteinase 14) is related to the pathophysiology of high-grade gliomas." (PMID 31661771, 2019). "Membrane type 1 matrix metalloproteinase (MMP14) originating from glioma cells was identified in qRT-PCR as the most highly up-regulated member of the MMP family of genes (~ 3 fold, p < 0.05) in this system." (PMID 27613828, 2016). "IL-6 was also the key cytokine inducing cytomembrane MMP14 expression, the active form of MMP14, in glioma cells." (PMID 27613828, 2016). "A growing body of evidence indicates that MMP14 is up-regulated in diverse aggressive tumor and stromal cells, and thus, MMP14 originating from microglia or glioma cells is emerging as a potential interventional target for glioma therapy." (PMID 27613828, 2016). "The previous experiment demonstrated that soluble factors promoted glioma migration and invasion through up-regulation of cytomembrane MMP14." (PMID 27613828, 2016). "Taken together, our results demonstrated that migration and invasion of glioma cells was promoted through increased MMP14 expression regulated by the secretion of IL-6 from astrocytes." (PMID 27613828, 2016). "Taken together, our results indicated that cytomembrane MMP14 was induced by IL-6 secreted from astrocytes, thereby enhancing the migration and invasion of glioma cells through activation of MMP2." (PMID 27613828, 2016). "Increased expression of IL-6 and MMP14 was first validated in primary human glioma specimens and then correlated with various clinical parameters." (PMID 27613828, 2016). "In order to further confirm a role for IL-6 in MMP14 up-regulation, IL-6 antibodies were used to block function in glioma cells in culture." (PMID 27613828, 2016). "The relationship between astrocytes and glioma cells was further dissected through the identification of IL-6 from protein arrays as a critical cytokine mediating an increase in cytomembrane MMP14." (PMID 27613828, 2016). "Both total protein and the cytomembrane form of MMP14 were increased in glioma cells stimulated with IL-6." (PMID 27613828, 2016). "The results indicated that astrocytes enhanced the migration and invasion potential of glioma, possibly through the secretion of IL-6 and increased MMP14." (PMID 27613828, 2016). "MMP14 protein levels were nearly completely abolished in glioma cells in the presence of IL-6 antibodies." (PMID 27613828, 2016). "Western blot analysis revealed an increase in the total protein for MMP14 in treated over untreated glioma cells." (PMID 27613828, 2016). "Glioma cells were therefore directly stimulated with IL-6 (50 ng/mL) to examine its role in MMP14 expression." (PMID 27613828, 2016). "MMP14 is more highly expressed in glioma than in normal cells, both in vitro and in vivo, and over-expression of MMP14 has been reported to enhance migration and invasion in glioma through several pathways." (PMID 27613828, 2016). "Using a transwell co-culture system, we found that astrocytes were able to induce MMP14 activity in glioma cells, thereby enhancing migration and invasion." (PMID 27613828, 2016).
glioma (continued). "In glioma cells HOXD10 also appears to have a tumor suppressive function as judged by repression of the invasion-related MMP-14 and uPAR genes." (PMID 25301728, 2014). "To demonstrate that MMP14 staining exhibits strong correlation with glioma progression, we performed an IHC staining of 98 specimens with MMP14 antibodies." (PMID 24156018, 2013). "To understand how the inhibition of MMP14 affects TMZ and XRT, we knocked down the expression of MMP14 in several glioma cell lines." (PMID 24156018, 2013). "In conclusion, we demonstrate that the attenuation of MMP14 inhibits glioma proliferation and improves therapeutic effect mediated by TMZ and XRT." (PMID 24156018, 2013). "Consistent with Marimastat inhibition data, silencing of MMP14 also induced G2/M arrest in all three glioma cell lines used in the study." (PMID 24156018, 2013). "Based on these findings, we suggest that miR-23a promotes glioma U251 cell and U87 invasion, probably by the regulation of MMP-14 via directly targeting HOXD10." (PMID 24305689, 2013). "To evaluate that, we treated glioma cells with a panel of MMP14 inhibitors CP101537, CP471474, and Marimastat, (Sigma-Aldrich Corp) that have previously been tested in treatment of glioma 22,23." (PMID 24156018, 2013). "The results are consistent with the data published earlier 21 and imply that both of these therapeutic modalities increase the level of MMP14 which correlates with survival of glioma patients." (PMID 24156018, 2013). "The treatment of gliomas with 100 nmol/L of Marimastat significantly inhibits the expression of MMP14 in U251, U87, GBM39, and GBM43 tumor cells." (PMID 24156018, 2013). "On the other hand, DHMEQ treatment was able to reduce in dose-dependent manner the expression of the metastasis-promoting genes MMP-2, MMP-14, TIMP-2, and uPA, all of which have been implicated in the regulation of invasion in glioma cells." (PMID 23533755, 2013). "In vivo genetic knockdown of MMP14 significantly decreased tumor growth of glioma xenografts and improved survival of glioma-bearing mice." (PMID 24156018, 2013). "Genetic silencing of MMP14 positively correlates with G2/M arrest and sensitizes glioma cells to TMZ and XRT in vitro and in vivo in an orthotopic glioma model." (PMID 24156018, 2013). "To establish the correlation between MMP14 expression and glioma grade, we stained a TMA containing 98 glioma samples with MMP14 antibodies in duplicates." (PMID 24156018, 2013). "More importantly, we found that miR-23a induced glioma cell invasion by modulating MMP-14 via its target HOXD10." (PMID 24305689, 2013). "Genetic knockdown of MMP14 in U87 and U251 glioma cells induced G2/M arrest and decreased proliferation." (PMID 24156018, 2013). "In our study, we show that MMP14 shRNA interference delays tumor formation in the U251 cells and completely inhibits glioma establishment in the U87 model." (PMID 24156018, 2013). "Of all the inhibitors tested, we found that Marimastat not only inhibits the expression of MMP14 in U87 and U251 glioma cells, but also induces cell cycle arrest." (PMID 24156018, 2013). "This overexpression promoted glioma cell invasion, probably by modulating MMP-14 via directly inhibiting the expression of HOXD10, which was identified as a novel target of miR-23a." (PMID 24305689, 2013). "Moreover, miR-10b-5p promotes glioma cell invasion by downregulating HOXD10 and upregulating invasion factors such as MMP14 and uPAR, highlighting the miR-10b-5p/HOXD10/MMP14/uPAR axis as a key driver of glioma malignancy." (PMID 39796267, 2025). "Furthermore, a dual-modality imaging probe targeting MMP-14, overexpressed in glioma cells, was developed." (PMID 39911388, 2025). "Additionally, TLR2 expression is induced in glioma-associated macrophages (GAM) by glioma cells provoking the transcription of MMP-9 and MMP-14, and cancer growth and spread." (PMID 38069210, 2023).